BCKDHA (branched chain keto acid dehydrogenase E1 subunit alpha)
Description:
Together with BCKDHB forms the heterotetrameric E1 subunit of the mitochondrial branched-chain alpha-ketoacid dehydrogenase (BCKD) complex. The BCKD complex catalyzes the multi-step oxidative decarboxylation of alpha-ketoacids derived from the branched-chain amino-acids valine, leucine and isoleucine producing CO2 and acyl-CoA which is subsequently utilized to produce energy. The E1 subunit catalyzes the first step with the decarboxylation of the alpha-ketoacid forming an enzyme-product intermediate. A reductive acylation mediated by the lipoylamide cofactor of E2 extracts the acyl group from the E1 active site for the next step of the reaction.
Synonyms: BCKDE1A; MSU; MSUD1; MSUD1A; OVD1A
Tractability: Small molecule: a structure with a bound ligand is known. PROTAC: ubiquitination databases record sites on it; its protein half-life has been measured.
Gene: Protein-coding gene on chromosome 19 (41,397,793 to 41,425,005, forward strand). Ensembl gene ENSG00000248098.
Subcellular location: Mitochondrion matrix
Pathways (Reactome):
Disease: Branched-chain ketoacid dehydrogenase kinase deficiency; H139Hfs13* PPM1K causes a mild variant of MSUD; Loss-of-function mutations in BCKDHA or BCKDHB cause MSUD; Loss-of-function mutations in DBT cause MSUD2; Loss-of-function mutations in DLD cause MSUD3/DLDD
Metabolism: BCKDH synthesizes BCAA-CoA from KIC, KMVA, KIV; Branched-chain amino acid catabolism
Gene Ontology:
Molecular function: branched-chain 2-oxo acid dehydrogenase activity; protein binding; carboxy-lyase activity; oxidoreductase activity, acting on the aldehyde or oxo group of donors, disulfide as acceptor
Biological process: branched-chain alpha-keto acid decarboxylation to branched-chain acyl-CoA; branched-chain amino acid catabolic process
Cellular component: branched-chain alpha-ketoacid dehydrogenase complex; mitochondrion; mitochondrial matrix
Genetic constraint (gnomAD): Loss-of-function variants: 43 observed, 51.05 expected, observed/expected ratio (o/e) 0.84, 90% interval 0.66 to 1.09. The upper end of that interval is the gene's LOEUF score, 1.09, which puts it in group 4 of 6, group 1 being the genes least tolerant of losing a copy. Missense variants: 527 observed, 642.1 expected, observed/expected ratio (o/e) 0.82, 90% interval 0.76 to 0.88. Synonymous variants: 234 observed, 254.18 expected, observed/expected ratio (o/e) 0.92, 90% interval 0.83 to 1.03.
Gene-disease validity (ClinGen):
ClinGen rates the evidence that BCKDHA causes each of these diseases.
maple syrup urine disease type 1A (autosomal recessive): Definitive. A maple syrup urine disease caused by mutations in BCKDHA.
Homologues: Orthologues: chimpanzee BCKDHA (98% identical), rabbit BCKDHA (94% identical), rat Bckdha (94% identical), guinea pig BCKDHA (93% identical), mouse Bckdha (93% identical), macaque TMEM91 (92% identical), dog BCKDHA (91% identical), pig BCKDHA (89% identical), tropical clawed frog bckdha (81% identical), zebrafish bckdha (77% identical), Caenorhabditis elegans bckd-1A (56% identical), Drosophila melanogaster BckdhA (55% identical). Paralogues in human: PDHA1 (24% identical), PDHA2 (23% identical).
Diseases named in the same sentence as BCKDHA in open-access papers:
BCKDHA is named in the same sentence as 28 diseases in open-access papers, as found by Europe PMC text mining. Sharing a sentence is not in itself a finding about the gene and the disease. The quoted sentences say what the papers report.
maple syrup urine disease (16 papers, 2013 to 2025). An autosomal recessive inherited disorder caused by mutations in the BCKDHA, BCKDHB, DBT, and DLD genes. "Maple syrup urine disease (MSUD) is a rare autosomal recessive metabolic disorder caused by variants in any of the following genes: BCKDHA, BCKDHB, and DBT gene." (PMID 39456016, 2024). "Maple syrup urine disease (MSUD) is an autosomal recessive inherited metabolic disorder caused by mutations in the BCKDHA, BCKDHB, DBT, and DLD genes." (PMID 29740478, 2018). "The alternative direct prediction of genes for oligogenic diseases with RWR (e.g. predicting DBT gene as associated to maple syrup urine disease using only BCKDHA and BCKDHB genes as seed) yielded an AUC of 0.85." (PMID 28715999, 2017). "Maple syrup urine disease (MSUD) is an autosomal recessive metabolic disorder originating from defects in the branched-chain α-ketoacid dehydrogenase (BCKDH) complex encoded by BCKDHA, BCKDHB and DBT." (PMID 38837343, 2024). "Pathogenic biallelic variants in the BCKDHA, BCKDHB, or DBT genes are responsible for the inborn error of metabolism known as Maple Syrup Urine Disease (MSUD)." (PMID 40710547, 2025). "Maple syrup urine disease (MSUD) is a rare autosomal recessive inherited disorder of branched‐chain amino acid metabolism caused by mutations in BCKDHA, BCKDHB, and DBT that encode the E1α, E1β, and E2 subunits of the branched‐chain α‐ketoacid dehydrogenase (BCKD) complex." (PMID 36341163, 2022). "For example, among the 19 diseases with ‘Ketosis’ as clinical sign, two of them were classified as oligogenic: maple syrup urine disease with 3 genes (BCKDHA, BCKDHB and DBT) and Permanent neonatal diabetes mellitus with 4 genes (GCK, INS, KCNJ11 and ABCC8)." (PMID 28715999, 2017). "Four of these decedents had compound heterozygous P/LP/VUS variants in genes associated with recessive disorders, including CFTR (cystic fibrosis), BCKDHA (maple syrup urine disease), MPDZ (congenital hydrocephalus-2), and GDAP1 (Charcot-Marie-Tooth disease, type 4A)." (PMID 38229148, 2024). "Maple syrup urine disease (MSUD) is an autosomal recessive disorder of branched chain amino acid (leucine, valine, isoleucine) catabolism due to branched-chain alpha-ketoacid dehydrogenase complex (BCKD) deficiency encoded by BCKDHA, BCKDHB, and DBT genes." (PMID 32752260, 2020). "Maple syrup urine disease is associated with mutation in DBT, BCKDHB, and BCKDHA genes." (PMID 25029527, 2014). "Sequence analysis of the three maple syrup urine disease (MSUD) genes, BCKDHA, BCKDHB, or DBT, in two unrelated cases of known biochemical diagnosis of MSUD detected only one familial mutation each." (PMID 24304607, 2013).
type 2 diabetes (3 papers, 2017 to 2025). "Furthermore, additional studies suggest that BCKDHA induces β-cell mitochondrial dysfunction, stress signal transduction, and cell apoptosis related to type 2 diabetes mellitus (T2DM)." (PMID 38601155, 2024). "Our data indicate that diabetic db/db mice may be a good model of type 2 diabetes, and are characterized by reduced muscle BCAA degradation due to a lower level of BCKDHA subunit complex, and increased levels of the transaminase (BCAT2)." (PMID 29062026, 2017).
heart failure (2 papers, 2022 to 2023). Inability of the heart to pump blood at an adequate rate to meet tissue metabolic requirements. "The transcriptome reprogramming observed in the BCKDHA-cKO hearts highlights the potential mechanisms involved in the contribution of BCAA catabolic defects to heart failure." (PMID 36991098, 2023). "Colocalization, gene expression profiling, and Mendelian randomization provide convergent evidence for the roles of BCKDHA and circulating branch-chain amino acids in heart failure and cardiac structure." (PMID 36376295, 2022).
liver cancer (2 papers, 2022 to 2025). An epithelial or non-epithelial malignant neoplasm that arises from the liver. "High expression of dephosphorylated BCKDHA and PPM1K promotes tumorigenesis, making BCKDHA and PPM1K potential therapeutic targets and predictive biomarkers for liver cancer." (PMID 40438606, 2025).
lung adenocarcinoma (2 papers, 2021 to 2023). A carcinoma that arises from the lung and is characterized by the presence of malignant glandular epithelial cells. "The copy numbers of both the target (CYP2C8, CYP3A4) and the reference genes (ALB, B2M, BCKDHA, F5, CD36, MPO, TBP, RPPH1) established in primary lung adenocarcinoma by the qPCR-based method were congruent with those determined by next-generation sequencing (for 10 genes, slope = 0.9498, r2 = 0.72)." (PMID 37686184, 2023).
Obesity (2 papers, 2016 to 2023). Accumulation of substantial excess body fat. "A novel APOE-interacting protein, BCKDHA, was identified, and its influence on BCKD activity in response to diet-induced obesity and dietary restriction was presented." (PMID 36749362, 2023).
diabetic cardiomyopathy (1 paper, 2021). Diabetic cardiomyopathy is a disorder of the heart muscle in people with diabetes. "BCKDHA mRNA levels were not significantly altered in diabetic cardiomyopathy mice but were increased by pyridostigmine." (PMID 34084135, 2021). "In addition, BCKDHA phosphorylation and BCKDK protein expression were increased, whereas BCAT2 and PP2Cm protein expression was decreased in diabetic cardiomyopathy mice." (PMID 34084135, 2021).
Hyperglycemia (1 paper, 2025). An increased concentration of glucose in the blood. "As revealed by protein quantification, BCKDHA and BCKDHB were downregulated in diabetic retinas and hyperglycemia-induced Müller cells, whereas BCKDK levels increased." (PMID 39150511, 2025).
ischemic stroke (1 paper, 2023). A stroke disorder caused by obstruction of blood flow to the brain, due to thrombotic (local blood clot formation) or embolic (due to a blood clot or other material traveling from another site) event. "In conclusion, our findings show that BCAA mediated neuronal ferroptosis in cerebral I/R injury by regulating BCKDHA Ser293 phosphorylation, providing new understanding of the biochemistry driving ferroptosis in ischemic stroke." (PMID 37752100, 2023).
leukopenia (1 paper, 2021). "Molecular biology verification results showed that Lvjiaobuxue granule can significantly reduce the key metabolic enzymes ACADS and BCKDHA in the catabolism of BCAAs, thereby playing a role in the treatment of leukopenia." (PMID 34759816, 2021). "In this study, two key enzymes, the BCKDHA and ACADS enzyme levels in leukopenia, significantly increased in the BCAAs catabolism pathway." (PMID 34759816, 2021).
melanoma (1 paper, 2024). A malignant, usually aggressive tumor composed of atypical, neoplastic melanocytes. "Recently, the enzyme BCKDHA, known as branched-chain keto acid dehydrogenase E1 subunit alpha, which is involved in branched-chain amino acid metabolism, has been found to regulate the expression of FASN and ATP-citrate lyase (ACLY) in melanoma." (PMID 38921444, 2024).
nephritis (1 paper, 2008). Inflammation of renal tissue. "Transcripts for BCKDHA and DBT, two enzymes in the branched chain amino acid metabolism pathway required for the catabolism of leucine, valine and isoleucine, are reduced in nephritis, perhaps leading to the accumulation of leucine in diseased tissue." (PMID 18980674, 2008).
pancreatic cancer (1 paper, 2025). "Furthermore, in both CC and CM, the high expression of BCKDHA not only serves as an energy source for cells but also suggests that the BCAA metabolic pathway may offer novel therapeutic targets for pancreatic cancer." (PMID 40422699, 2025).
metabolic disorder (5 papers, 2018 to 2024). "Collectively, these results confirm that PPM1K mediated-BCKDHA S293 phosphorylation contributed to BCAA metabolic disorder 24 h after cerebral I/R and could be ameliorated by BT2." (PMID 37752100, 2023).
tumor (4 papers, 2019 to 2024). "To determine the effect of BCKDHA on tumor growth, we subcutaneously injected 8988 T cells expressing control shRNA (shGFP) or BCKDHA shRNA (shBCKDHA) into mice to construct a xenograft mouse model." (PMID 31784505, 2019). "BCKDHA knockdown had a significant inhibitory effect on tumor growth." (PMID 31784505, 2019). "Compared with normal mouse liver tissues, the expression of BCAT2 was higher, while the expressions of BCKDHA and DBT were lower in the tumor tissues of DEN and CCl4-induced HCC mouse models." (PMID 38580754, 2024). "In contrast, an investigation revealed that in breast cancer, along with BCAT1, the expression of BCKDHA and BCKDHB was upregulated, thus promoting tumor cell growth." (PMID 37637065, 2023). "The sum of the scores for these genes was higher than 5 or lower than −5 except for BCKDHA and CD36 in liver metastasis; therefore, in the particular tumour sample, these genes were considered to be inappropriate for normalization of the number of gene copies." (PMID 37686184, 2023).
BCKDHA also shares sentences with these, for which no sentence is quoted: autosomal recessive inherited disorder (1 paper); biotinidase deficiency (1); Charcot-Marie-Tooth disease type 4A (1); colon cancer (1); cystic fibrosis (1); Hartnup disease (1); liver fibrosis (1); Methylmalonic aciduria (1); mitochondrial disease (1); neonatal diabetes mellitus (1); pontocerebellar hypoplasia type 6 (1); type 2 diabetes mellitus (1); type I citrullinemia (1).